RPL28 (ribosomal protein L28)
Description:
Component of the large ribosomal subunit. The ribosome is a large ribonucleoprotein complex responsible for the synthesis of proteins in the cell.
Synonyms: FLJ43307; L28; eL28
Tractability: Small molecule: an approved drug acts on it; a structure with a bound ligand is known; a high-quality ligand is known. PROTAC: UniProt records ubiquitination sites on it; ubiquitination databases record sites on it; its protein half-life has been measured; a small molecule that binds it is known. Other modalities: a drug acting on it is in phase 2 or 3 trials.
Target class: Other cytosolic protein
Gene: Protein-coding gene on chromosome 19 (55,383,856 to 55,403,250, forward strand). Ensembl gene ENSG00000108107.
Subcellular location: Cytoplasm
Subcellular location (Human Protein Atlas): Cytosol; Endoplasmic reticulum
Pathways (Reactome):
Metabolism of proteins: Eukaryotic Translation Termination; Formation of a pool of free 40S subunits; GTP hydrolysis and joining of the 60S ribosomal subunit; L13a-mediated translational silencing of Ceruloplasmin expression; PELO:HBS1L and ABCE1 dissociate a ribosome on a non-stop mRNA; Peptide chain elongation; Ribosome Quality Control (RQC) complex extracts and degrades nascent peptide; SRP-dependent cotranslational protein targeting to membrane; ZNF598 and the Ribosome-associated Quality Trigger (RQT) complex dissociate a ribosome stalled on a no-go mRNA
Metabolism of RNA: Major pathway of rRNA processing in the nucleolus and cytosol; Nonsense Mediated Decay (NMD) enhanced by the Exon Junction Complex (EJC); Nonsense Mediated Decay (NMD) independent of the Exon Junction Complex (EJC)
Cellular responses to stimuli: Response of EIF2AK4 (GCN2) to amino acid deficiency
Developmental Biology: Regulation of expression of SLITs and ROBOs
Disease: Viral mRNA Translation
Metabolism: Selenocysteine synthesis
Gene Ontology:
Molecular function: protein binding; RNA binding; structural constituent of ribosome
Biological process: cytoplasmic translation; negative regulation of myoblast fusion; spermatogenesis; striated muscle contraction; translation
Cellular component: cell body; cytoplasm; cytoplasmic ribonucleoprotein granule; cytosol; cytosolic large ribosomal subunit; cytosolic ribosome; dendrite; endoplasmic reticulum; extracellular exosome; membrane; ribosome; synapse
Genetic constraint (gnomAD): Loss-of-function variants: 4 observed, 12.77 expected, observed/expected ratio (o/e) 0.31, 90% interval 0.15 to 0.72. The synonymous counts are far from expectation, so gnomAD's model fits this gene poorly and the ratio says little. Missense variants: 214 observed, 187.47 expected, observed/expected ratio (o/e) 1.14, 90% interval 1.02 to 1.28. Synonymous variants: 91 observed, 67 expected, observed/expected ratio (o/e) 1.36, 90% interval 1.14 to 1.62.
Homologues: Orthologues: dog RPL28 (99% identical), guinea pig Rpl28 (99% identical), mouse Rpl28 (99% identical), pig RPL28 (98% identical), rat Rpl28l2 (93% identical), tropical clawed frog rpl28 (80% identical), zebrafish rpl28 (79% identical), Drosophila melanogaster RpL28 (46% identical), Caenorhabditis elegans rpl-28 (36% identical).
Diseases named in the same sentence as RPL28 in open-access papers:
RPL28 is named in the same sentence as 19 diseases in open-access papers, as found by Europe PMC text mining. Sharing a sentence is not in itself a finding about the gene and the disease. The quoted sentences say what the papers report.
colorectal cancer (3 papers, 2021 to 2024). A primary or metastatic malignant neoplasm that affects the colon or rectum. "In the context of gastric cancer, RPL15, RPL6 and RPS13 exhibited upregulated expressions, while in colorectal cancer, RPS18, RPS23, RPL28 and RPL32 were found to be downregulated, implicating these ribosomal proteins as potential diagnostic markers for gastric and colorectal cancers, respectively." (PMID 39684863, 2024). "RPL28 is related to the prognosis of colorectal cancer by participating in immune remodulation." (PMID 37763280, 2023).
hepatocellular carcinoma (3 papers, 2021 to 2026). A malignant tumor that arises from hepatocytes. "The expression of sorafenib-resistant associated gene RPL28 in Morris Hepatoma was determined by real time qPCR." (PMID 34307151, 2021). "We identified that RPL28 gene is involved in sorafenib resistance in hepatocellular carcinoma." (PMID 34307151, 2021). "Furthermore, it was found that both RNA and protein expression of RPL28 increased in HepG2 sorafenib-resistant specimens of Morris Hepatoma rats." (PMID 34307151, 2021).
metastatic colorectal cancer (2 papers, 2019 to 2020). "The mutation of RPL28 was associated with shorter progression-free survival and overall survival in metastatic colorectal cancer." (PMID 33133154, 2020).
colon cancer (1 paper, 2019). "In the TCGA cohort, RPL28 expression was significantly higher by 124% (P < 0.001) in colon tumors compared to paired normal tissues." (PMID 31506518, 2019). "Repression of RPL28 reduced proliferation by 1.4-fold to 5.6-fold (P < 0.05) in colon cancer HCT116 and HT-29 cells." (PMID 31506518, 2019). "In support of this notion, repression of RPL28 was shown to significantly impair cell proliferation of HCT116 and HT-29 colon cancer cell models, suggesting that RPL28 higher expression may be associated to a more aggressive phenotype." (PMID 31506518, 2019).
colorectal tumors (1 paper, 2019). "RPL28 expression was higher in colorectal tumors compared to paired normal tissues by up to 124% (P < 0.001) in three independent datasets." (PMID 31506518, 2019).
Obesity (1 paper, 2022). Accumulation of substantial excess body fat. "We identified two other DMRs in genes RPL28 and PANCR that have not previously been associated with adipogenesis or lower birth weight before but have appeared in several obesity or metabolism related studies." (PMID 35216435, 2022).
tumor (4 papers, 2016 to 2026). "We further established that high RPL28 tumor expression is linked to a reduced survival of mCRC patients, possibly through an enhanced tumor growth and a remodelling of the expression of ECM and immunoglobulin pathways." (PMID 31506518, 2019). "Our analysis of transcriptomic changes associated with high RPL28 tumor expression in mCRC patients suggested an upregulation of several genes of immunoglobulins, proposing the involvement of the complement system." (PMID 31506518, 2019). "This polymorphism was also associated with an increased expression of RPL28 in colon tissue of healthy donors, and its expression was further increased in tumor tissues compared to paired normal tissues." (PMID 31506518, 2019). "We report that the germline variant rs4806668G > T in RPL28 and tumor expression of this gene are associated with survival of mCRC patients." (PMID 31506518, 2019). "In two other independent cohorts of mCRC, higher RPL28 tumor expression level was associated with poor survival." (PMID 31506518, 2019). "Overall, it may be envisioned that the changes in gene expression associated with RPL28 activate cancer-related signaling pathways and exert tumor-promoting activities in mCRC patients." (PMID 31506518, 2019). "Metastatic cases with highest RPL28 tumor expression had a reduced survival in two datasets (n = 88, P = 0.009 and n = 56, P = 0.009)." (PMID 31506518, 2019). "Based on the dichotomization at the median expression levels, mCRC patients from the TCGA cohort with high tumor expression of RPL28 had a reduced survival compared to those with low levels (n = 88, P = 0.009)." (PMID 31506518, 2019). "The other ribosomal protein gene transcripts identified in mouse mammary gland to correlate with ZFAS1, i.e. RPS21, RPS24, RPL22 and RPL28, showed significant expression differences between normal and tumour samples (*P < 0.05, **P < 0.01, ***P < 0.001, ****P < 0.0001)." (PMID 27871336, 2016).
cancer (3 papers, 2019 to 2026). A tumor composed of atypical neoplastic, often pleomorphic cells that invade other tissues. "Furthermore, RPLP1 and RPL28 expression in BKZ-8 was affected by KJ-Pyr-9 application, suggesting an involvement of MYC signaling in ribosomal biosynthesis of AC-derived LCSC-like cells, as already shown for several cancer types." (PMID 33925297, 2021).
infection (2 papers, 2014 to 2022). The state of being infected such as from the introduction of a foreign agent such as serum, vaccine, antigenic substance or organism. "In contrast, the biological processes downregulated with infection include ribosomal biogenesis (Rpl3, Rpl37, Rps5, Rpl11, Rplp1, Rpl28, Rpl19, Rps28, Rps14)." (PMID 35789215, 2022).
RPL28 also shares sentences with these, for which no sentence is quoted: autism spectrum disorder (1 paper); Brachycephaly (1); breast carcinoma (1); coenzyme Q10 deficiency (1); developmental delay (1); epilepsy (1); Myelodysplasia (1); prostate carcinoma (1); trichomegaly (1); ZIKV infection (1).